CXCL1 (C-X-C motif chemokine ligand 1)
Diseases named in the same sentence as CXCL1 in open-access papers (continued):
Sharing a sentence is not in itself a finding about the gene and the disease.
gastric cancer (continued). "Immunohistochemistry analysis of tumor samples from gastric cancer patients has shown that high expression of CXCL1 is correlated with inferior survival and metastatic tendencies." (PMID 36612163, 2022). "In gastric cancer, overexpression of the CXCL1–CXCR2 axis is closely associated with the migration and invasiveness of malignant cells, and CXCL1 release by the lymphatic endothelium promotes lymph node metastasis." (PMID 34195201, 2021). "CXCL1 promotes tumor growth through VEGF pathway activation and is associated with inferior survival in gastric cancer." (PMID 33767987, 2021). "Aberrant chemokine CXCL1 and CXCL8 expression in CAFs was closely associated with tumor progression and poorer survival in gastric cancer patients." (PMID 35011369, 2021). "Chemokine (C-X-C motif) ligand 1 (CXCL1) secreted by tumor-associated lymphatic endothelial cells induces integrin β1 to activate FAK/Akt signaling and promotes adhesion and metastasis of gastric cancer via MMP2/9 upregulation." (PMID 33406733, 2021). "Gastric cancer extracellular vesicles transfer various miRNAs and induce chemokines such as CXCL1 and CXCL8 expression in CAFs." (PMID 35011369, 2021). "In gastric cancer patients, high CXCL1 expression correlated with invasion and lymph node metastasis." (PMID 34503058, 2021). "CXCL1 has also been demonstrated to play an important role in gastric cancer progression and cell migration." (PMID 32132577, 2020). "Gastric cancer cells induce expression of CXCL1 in LECs, which subseqently drives tumor lymphangiogenesis and lymphogenous metastasis." (PMID 31105685, 2019). "In gastric cancer, LECs upregulated expression of CXCL1, which in turn increased tumor cell invasiveness via CXCR2 and stimulated lymphangiogenesis." (PMID 31105685, 2019). "CXCL1 can also activate the integrin β1/FAK/AKT or FAK-ERK1/2-RhoA signaling pathway to promote gastric cancer cell migration to the lymphatic system." (PMID 30158589, 2018). "Among the 270 gastric cancers examined, 144 cases (53%) were positive for CXCL1 expression in cancer cells, and 113 cases (42%) were positive for CXCR2 expression in stromal cells." (PMID 28575019, 2017). "We currently reported that CXCL1 from gastric cancer cells stimulates CXCR2 signalling of BM-MCs which become myofibroblasts in tumor stroma using cell lines." (PMID 28575019, 2017). "CXCL-1 overexpression was also found to be significantly closely with gastric cancer progression and poor survival." (PMID 29109519, 2017). "CXCL-1 depletion was capable of inhibiting the migration and invasion ability of gastric cancer cells." (PMID 29109519, 2017). "CXCL1 was expressed in the cytoplasm of gastric cancer cells, and CXCR2 was expressed on the cell membrane and in the cytoplasm of fibroblasts." (PMID 28575019, 2017). "CXCL1 is a chemokine that has roles in development, homeostasis and the immune system and its expression was significantly higher in serum samples of gastric cancer patients in comparison to healthy donors." (PMID 29283424, 2017). "The correlations between the clinicopathological features of 270 primary gastric carcinomas and CXCL1 in cancer cells and CXCR2 in stromal cells were analyzed in immunohistochemical studies." (PMID 28575019, 2017). "Hs738 cells secreted IL-6 and CXCL1 more than did gastric cancer cell lines with the exception of MKN-1." (PMID 25785838, 2015). "For instance, CXCL1 depletion reduced the migration and invasion of gastric cancer cells and an anti-CXCL1 antibody inhibited growth of human pancreatic cancer cells." (PMID 24376747, 2013). "In the IHC study, a positive significant correlation between GLO1 and CXCL1 expression patterns was observed in resected specimens of gastric cancer." (PMID 22479608, 2012). "Earlier studies by our group have shown that SPARC, CLIC1, SLPI, CXCL1, CXCL8, and CXCR2 are highly expressed and associated with advanced stages and poor prognosis of gastric cancer." (PMID 22479608, 2012).
gastric cancer (continued). "Based on these findings, we propose that GLO1 mediates gastric cancer cell migration and invasion at least partially mediated through activation of CXCL1, CXCL8, and VEGF." (PMID 22479608, 2012). "Gastric cancer cells secrete TNF-α to induce release of CXCL1 and CXCL5 from macrophages." (PMID 41583453, 2025). "Gastric cancer cells secrete TNF-α to induce macrophages to release CXCL1 and CXCL5." (PMID 41583453, 2025). "CXCL1 regulates host defense against pathogens through multiple pathways and plays an important regulatory role in the transformation, growth, and angiogenesis of gastric cancer cells." (PMID 37324920, 2023). "The increased expression of CXCR2 ligands is higher in gastric epithelial cells than in gastric cancer cells, which shows that CXCL1 may be significant in the early stages of tumor formation." (PMID 37408240, 2023). "CXCL1 gene expression was detected in gastric cancer cell lines and gastric cancer mouse tissue." (PMID 36614235, 2023). "Furthermore, the same studies revealed an upregulation of circulating CXCL1 levels in patients with gastric cancer compared to the healthy controls." (PMID 36614235, 2023). "As one of the risk factors for developing gastric cancer is age, there may be a link between CXCL1, age, and gastric cancer." (PMID 37408240, 2023). "Gastric cancer tissues show a differential expression of CXCL1 and its receptor CXCR2." (PMID 36614235, 2023). "Many studies have pointed out that H. pylori infection can cause the abnormal expression of inflammatory cytokines IL‐6, IL‐8, and CXCL‐1, participate in the production and regulation of intestinal inflammatory diseases, and promote the development of gastric ulcer and even gastric cancer." (PMID 37324920, 2023). "Since epigenetic events such as DNA methylation happen early in the sequence; H. pylori-induced CXCL1 hypomethylation could likely be detected at an early stage of gastric cancer development." (PMID 36614235, 2023). "Additionally macrophages are also the major sources of chemokines and chemokine receptors in the gastric cancer microenvironment, such as CXCL1 and CXCL5, and promote migration through activating the CXCR2/STAT3 feed-forward circuit." (PMID 33112406, 2020). "Previously, we reported that CXCL1 secreted from gastric cancer cells might play an important role for the migration activity of BM-MCs via CXCL1/CXCR2 signaling." (PMID 28575019, 2017). "CXCL-1 secreted from lymphatic endothelial cells could promote gastric cancer migration, invasion and adhesion abilities via activating integrin β1/FAK/AKT signaling." (PMID 29109519, 2017). "Our previous report and this study might suggest the significance of CXCL1/CXCR2 axis on the progression of gastric cancer via the crosstalk between CXCL1 from cancer cells and CXCR2 of stromal fibroblasts." (PMID 28575019, 2017). "Therefore, we focused on CXCL1 expression in gastric cancer cells and CXCR2 expression in stromal fibroblast cells in this study." (PMID 28575019, 2017). "Moreover, elevated GLO1 and concomitant CXCL1 over-expression in patients with gastric cancer were significantly correlated with survival." (PMID 22479608, 2012). "In this study, we indicated that CXCL1 plays a crucial role in the gastric cancer microenvironment, as it might play an essential role in the progress of cancers, mainly by promoting invasion and metastasis, which are the most common causes of cancer progression." (PMID 36614235, 2023). "However, the CXCL1/CXCL8-CXCR2 axis may also cooperate with other chemokines in gastric cancer cell migration, particularly C-X-C motif ligand 12 (CXCL12, stromal-derived factor-1 (SDF-1))-CXCR4." (PMID 37408240, 2023). "Further, gastric cancer cells secrete extracellular vesicles that alter the expression of various genes in different cells in the tumor niche, for example extracellular vesicles that contain miR-155, miR-193b and miR-210, inducing the expression of chemokines CXCL1 and CXCL8 in fibroblasts." (PMID 37408240, 2023).
gastric cancer (continued). "In addition, as serum levels of CXCL1 are elevated in gastric cancer patients, plasma CXCL1 levels may be a marker of gastric cancer." (PMID 37408240, 2023). "Our present results might be explained as follows: CXCL1 secretion by gastric cancer cells occurs first and subsequently stromal cells with CXCR2 expression are recruited into the tumor microenvironment, which is consistent with our previous in vitro and in vivo findings." (PMID 28575019, 2017). "Several identified hub genes, including CXCL1, CCL20, IL12B, STAT4, and CD80, are involved in chemokine signaling, immune modulation, and inflammation, which can promote H. pylori–mediated gastric cancer." (PMID 40445003, 2025). "CXCL1/CXCR2 signaling promotes the recruitment and accumulation of PMN-MDSCs in gastric cancer, leading to CD8+ T-cell exhaustion." (PMID 41051525, 2025). "Specifically, VCAM1 elevates the expression of CXCL1 via the activation of the AKT-mTOR pathway, which subsequently promotes the recruitment and infiltration of human gastric cancer-derived mesenchymal stem cells and M2 macrophages." (PMID 39876839, 2025). "CXCR4, SPP1, CXCL1, MMP9, and TIMP1 were up-regulated and NFE2L2 was down-regulated in gastric cancer cell lines compared with control." (PMID 38221932, 2024). "Gastric cancers have been shown to have higher levels of CXCL8, while renal cell carcinomas have been shown to have higher levels of CXCL1/3/5/8, which enhances angiogenesis and tumorigenesis." (PMID 38515019, 2024). "Activation of CXCR2 by CXCL1 and CXCL8 stimulates the proliferation of transformed cells, which leads to gastric cancer." (PMID 37408240, 2023). "CXCL1 and MMP7 showed the most significant and highest differential upregulation in gastric cancer samples compared to the healthy stomach." (PMID 36614235, 2023). "We show that the infection of KDM4B-knockdown cells led to the reduced production of IL-8 as well as CXCL1 and CCL5, which are chemokines involved in gastric cancer progression." (PMID 30683841, 2019). "Clinically, aberrant activation of CXCL1 and CXCL8 in CAFs correlated with poorer survival in gastric cancer patients." (PMID 31147602, 2019). "In contrast, our study reported the role of cancerous CXCL1 expression and CXCR2 expression of stromal fibroblasts in gastric cancer." (PMID 28575019, 2017). "CXCL1 and CXCR2 are expressed in both gastric cancer cells and stromal cells including fibroblasts and macrophages in our study." (PMID 28575019, 2017). "The expressions of CXCL1 in cancer cells and CXCR2 in stromal cells are useful prognostic factors for gastric cancer patients." (PMID 28575019, 2017). "Both CXCL1 expression in cancer cells and CXCR2 expression in stromal cells were independent prognostic factors for gastric cancer patients." (PMID 28575019, 2017). "Correlation between the expression of CXCL1 in cancer cells and that of CXCR2 in stromal cells and clinicopathologic features in 270 patients with gastric carcinoma." (PMID 28575019, 2017). "The levels of CXCL1 and IL8 secreted are consistent with those of other human colorectal and gastric cancer cell lines." (PMID 26104296, 2015). "Coexpression of CXCL1 and CXCR2 acts like an autocrine or paracrine mechanism to actuate metastasis of gastric cancer." (PMID 26497045, 2015). "In our experiments, levels of both HIF-1α and NF-κB were reduced in nuclei upon GLO1 silencing in gastric cancer cell lines, along with downstream target genes (VEGF, CXCL1, CXCL8, MMPs)." (PMID 22479608, 2012). "Additionally, macrophages serve as major sources of CXCL1 and CXCL5 in the gastric cancer microenvironment, and promote the migration of gastric cancer cells by activating a CXCR2/STAT3 feed-forward loop." (PMID 41583453, 2025).
gastric cancer (continued). "Previous studies have shown that H3K18la-mediated VCAM1 expression promotes gastric cancer progression and metastasis via the AKT‒mTOR‒CXCL1 axis; lactic acid accumulation resulting in H3K18la promotes PD-L1 transcription, thereby mediating the immune escape of gastric cancer cells." (PMID 40796546, 2025). "Chemokines CXCL1 and CXCL5 in macrophages are critical in gastric cancer metastasis." (PMID 38887558, 2024). "Using the top eight upregulated genes (SLPI, PLA2G2A, CXCL1, CCL20, REG1A, CLDN7, PI3, LGALS3) as a representative gene set for the high metabolic subcluster, we calculated the GSVA score of this gene set for each patient in the TCGA gastric cancer cohort." (PMID 38831933, 2024). "Gastric cancer cells secrete TNF-α, which increases CXCL1 expression in TAM." (PMID 37408240, 2023). "In addition, miR-204 has also been found to inhibit the proliferation of gastric cancer cells by targeting CKS1B, CXCL1, and GPRC5a." (PMID 34950208, 2021). "For example, CXCL1 expression was upregulated in gastric cancer tissues when compared with adjacent noncancerous tissues." (PMID 31803057, 2019). "A combination of CXCL1 and CXCR2 expression might thus be a useful prognostic indicator, especially for stage I gastric cancer patients." (PMID 28575019, 2017). "For the first time, we identified that CKS1B, CXCL1, and GPRC5A are putative targets of miR-204 and elucidated that miR-204 acted as potential tumor suppressor and, therefore, are useful as a promising therapeutic target for gastric cancer." (PMID 29283424, 2017). "It was found that CXCL1/CXCR2 recruits PMN-MDSCs, and S100A8/A9 increases CXCL1 expression in gastric cancer (GC) through the TLR4/p38 MAPK/NF-κB pathway." (PMID 39990210, 2025). "In addition, the expression of CXCL1 mRNA and protein was higher in human gastric cancer tissue compared with paired non-cancerous gastric tissues." (PMID 36614235, 2023). "Actually IL-6 increased the growth of all the gastric cancer cell lines except MKN-45; in contrast, CXCL1 did not affect their growth." (PMID 25785838, 2015).
lung cancer (57 papers, 2011 to 2025). A malignant neoplasm involving the lung. "CXCL1 also causes the migration of lung adenocarcinoma cancer cells and is important in lung cancer metastasis." (PMID 38673949, 2024). "One of the identified chemokines is CXCL1, which has been described to promote lung cancer growth through the recruitment of tumor-associated neutrophils." (PMID 34671021, 2021). "CXCL1 contributes to tumor-associated neutrophils infiltration in lung cancer which promotes tumor growth." (PMID 32730361, 2020). "Tumor-derived CXCL1 contributes to tumor-associated neutrophils infiltration in lung cancer which promotes tumor growth." (PMID 31998654, 2019). "Previous studies demonstrated that lung cancer with a KRAS mutation showed increased numbers of neutrophils through the expression of CXCL-1 and CXCL-2." (PMID 27483433, 2016). "Stromal cell-derived factor-1 is associated with tumor recurrence, and CXCL-1/2 mediate the chemoresistance in lung cancer." (PMID 25871388, 2015). "The released CXCL1 was functionally linked to recruiting monocytes into lung cancer cell microenvironment." (PMID 23665907, 2013). "CXCL-1 added to the tumour-linked neutrophils infiltration in lung cancer." (PMID 34336101, 2021). "For example, CXCL-1/2 is associated with chemoresistance in lung cancer." (PMID 31750252, 2019). "Although the number of fibroblasts in the human samples was limited, we corroborated some in vitro data, including increased expression of CXCL1 in the KRASG12D-driven versus non–KRAS-driven lung cancer samples." (PMID 39782689, 2025). "We also assessed expression changes for genes that change during lung cancer progression, including Cxcl1, Tgfa, and Tgfb1." (PMID 39782689, 2025). "S2D), which is in good agreement with previous reports that CXCL1 levels correlate with high tumor burden and poor prognosis in mouse models and patients with lung cancer." (PMID 39485842, 2024). "In lung cancer tumors, myofibroblasts cause the unfolding of the type III domains of fibronectin; the modified fibronectin increases CXCL1 expression in lung fibroblasts." (PMID 38673949, 2024). "CXCL1 expression is elevated in tumors of various types of lung cancer, including atypical lung cancer, lung adenocarcinoma, and NSCLC." (PMID 38673949, 2024). "These cells start producing CXCL1 under the influence of lung cancer cells, as shown by experiments on these cells cultured with NSCLC cells." (PMID 38673949, 2024). "Mechanistically, IGFBP2 stimulated the transcriptional activity of STAT3 on CXCL1, leading to an upregulation of CXCL1 expression in lung cancer cells and subsequently promoting gefitinib resistance." (PMID 38918360, 2024). "Mechanistically, IGFBP2 can activate STAT3 to enhance the transcriptional activity of CXCL1, thereby increasing the intracellular expression level of CXCL1, which contributes to the survival of lung cancer cells in the gefitinib environment." (PMID 38918360, 2024). "In lung cancer, only CXCL1 among the CXC chemokine subfamily was found to be significantly differentially expressed in the blood of patients with localized or systemic recurrence." (PMID 38918360, 2024). "CAFs in the lung cancer have been shown to express high levels of neutrophil chemoattractants, such as IL-6, IL-8, and CXCL1, and further support neutrophil recruitment by increasing their surface expression of VCAM and ICAM2." (PMID 35158807, 2022). "Elevated expression of CXCR2 ligands (CXCL1, 2, 3, 5, 6, 7, and 8) is observed in various tumor types, such as lung cancer, hepatocellular carcinoma, renal cell carcinoma, and melanoma." (PMID 35158807, 2022). "During tumourigenesis, tumourigenic signals such as Cxcl1 and Ccl2 induce Pdia4 overexpression and Stat3 phosphorylation and, subsequently, lead to an up‐modulation of Vegf proteins in lung cancer stromata." (PMID 35170261, 2022).